CXCL10 (C-X-C motif chemokine ligand 10)
Diseases named in the same sentence as CXCL10 in open-access papers (continued):
Sharing a sentence is not in itself a finding about the gene and the disease.
viral infection (continued). "CXCL10 has been implicated in SARS-CoV and other viral infections such as rhinovirus, respiratory syncytial virus (RSV), Coxsackie virus, hepatitis virus B and C, Ebola, dengue (DENV), and equine infectious anemia virus (EIAV)." (PMID 34582497, 2021). "As expected from the delay in the start of viral replication, CXCL10, and CCL5 responses were delayed in the brainstem compared with the lungs, reflecting the discrepancies in cell susceptibility to viral infection in the two tissues." (PMID 34608167, 2021). "Neutrophils can respond to viral infections using a CXCR-3-dependent mechanism after epithelial CXCL10 is released." (PMID 33946935, 2021). "Elevated levels of CXCL-10 have been reported in both the plasma and bronchial alveolar lavage fluid (BALF) and were associated with disease severity in viral infections." (PMID 34745109, 2021). "Chiefly amongst these, CCL3 (macrophage inflammatory protein-1α; MIP-1α), CCL4, CCL5, CXCL8, and CXCL10 are broadly expressed in the context of several (murine/human) viral infections." (PMID 34835105, 2021). "Interferons (IFNs) play a crucial role in the induction of some of these cytokines, such as CXCL10, as well as controlling viral infections." (PMID 34162308, 2021). "Among CXCL chemokines which are produced during viral infection, CXCL10 expression is observed in many viral infections." (PMID 32231656, 2020). "In total 20 ISGs were significantly upregulated in the RSV-infected mice compared to the non-infected mice and some of the top 10 upregulated genes, such as Irf7,Cxcl10, Ccl2, and Ccl4, are all ISGs known to be induced in response to viral infections." (PMID 33363532, 2020). "In this context, gene expression signatures in the lungs of SARS-CoV-2-infected patients who succumb to viral infection showed high expression of MCP-1/CCL2 and IP-10/CXCL10, which was linked to type I and II IFN responses." (PMID 33257679, 2020). "While expression of Ifnb1 and Cxcl10 was increased in peritoneal exudate cells 12 hr after virus infection in WT mice, such response was diminished in Stinggt/gt mice." (PMID 32886065, 2020). "More interestingly, it ascertains the safety of introducing new therapies (i.e., including those targeting CXCL-10) likely to dampen the host inflammatory response at this stage of the viral disease." (PMID 33138839, 2020). "IP10/CXCL10 is secreted in response to interferon gamma which is produced as part of the Th1 response to viral infection." (PMID 32116981, 2019). "To confirm these results we also studied by qPCR mRNA production of IFNβ and IFNβ-dependent genes such as Isg15, CXCL10 (an established marker of viral infection) or MX1." (PMID 29958295, 2018). "For FEV1/FVC, FEF25–75 and PEF, statistically significant interactions between viral infection and inflammation were seen for CXCL10 mRNA." (PMID 30463560, 2018). "Augmented serum levels of CXCL10 have been found during severe clinical manifestations of dengue and yellow fever." (PMID 29768624, 2018). "Previous studies have implicated activated microglia in leukocyte recruitment into the brain upon virus infection, and showed that antibodies to CXCL10 and CCL2 (MCP-1) reduce the migration of murine splenocytes toward HSV-infected microglia in vitro." (PMID 30027450, 2018). "Recent evidence points toward non-redundant roles for three IFN-induced CXCR3 ligands in vivo, for example, CXCL10 during viral infections and CXCL11 during allergic reactions." (PMID 30473680, 2018). "Previous studies have shown that hepatocytes produce a number of chemokines, such as MCP-1, CXCL-1 and CXCL-10, which are upregulated after viral infection or liver injury and play an important role in the induction of hepatic inflammatory responses." (PMID 29867111, 2018). "For FEV1, statistically significant interactions between viral infection and inflammation were seen for CXCL10 and TLR3 mRNA, IL-4 and CCL24 levels." (PMID 30463560, 2018).
viral infection (continued). "For FVC, statistically significant interactions between viral infection and inflammation were seen for CXCL10 mRNA, TLR3 mRNA, IL-4, IL-13, CCL5, CCL20 and CCL24." (PMID 30463560, 2018). "At day 2 postinfection, both TNF-α and IL-6 transcripts were moderately induced by wild-type virus, while CCL2, CCL4, CXCL9, and CXCL10 mRNA levels were all highly elevated by wild-type virus infection." (PMID 29138302, 2017). "Microglial cells have been shown to produce high levels of the chemokines CXCL9 and CXCL10 in response to viral infection." (PMID 28407741, 2017). "Previous studies suggest the prime role of neuronal CXCL10 production in recruitment of T cells in response to neurotropic viral infection such as rabies virus and West Nile virus." (PMID 26676825, 2016). "On the other hand, chemokines CCL-5 and chemokine (C-X-C motif) ligand-10 (CXCL-10) moderately increased post-virus infection." (PMID 27446066, 2016). "Microglial cells were found to produce high levels of CXCL9 and CXCL10 in response to viral infection, while infected astrocyte cultures produced markedly lower levels." (PMID 27207308, 2016). "Specifically, we show that immune perturbations induced by chronic viral infection can be rapidly reset following therapeutic intervention with DAAs, and provide insight into the regulation of sDPP4 activity and CXCL10 forms." (PMID 26181438, 2015). "While dsRNA was used in this study to simulate a viral infection, it is important to note that it, in and of itself, can also be involved in synergistic induction of CXCL10 in airway epithelial cells." (PMID 25033426, 2014). "Neuronal CXCL10 production has been shown to play a role in recruiting leukocytes to clear viral infections in the brain, such as during WNV encephalitis." (PMID 24802239, 2014). "Chemokines, such as CXCL10, are also produced by neurons in response to viral infections, such as West Nile viral infections." (PMID 24802239, 2014). "In this study, we demonstrate the synergistic stimulation of CXCL10 mRNA and protein, a key chemokine responsible for the early immune response to viral infection, following treatment of airway epithelial cells with IFN γ and influenza virus." (PMID 25033426, 2014). "Increased expression of CXCL10 has been reported in a number of virus infections including influenza, HIV, West Nile virus and Nipah virus." (PMID 24083897, 2013). "The mRNAs encoding IFNβ-dependent genes, such as IRF7, IFNα4, and IFNα6, as well as CXCL10 an established marker of viral infection, were also suppressed in DEAF1−/− MEFs." (PMID 23846693, 2013). "CXCL10 is part of the group of interferon-stimulated genes and it plays an important role during different viral infections by induction of cell activation, chemotaxis and lymphocyte priming toward the Th1 phenotype." (PMID 24083897, 2013). "In support of this, CXCL10-knockout mice have decreased ability to control viral infections, and show impaired T cell recruitment and activation, while CXCL10 transgenic mice show improved control of infection and enhanced NK cell responses." (PMID 22808255, 2012). "These cytokines which mainly included IL2, IL1, CXCL10 and RANTES were reported to be involved in cytokine-storm in response to viral infection in humans and thus associated with H5N1 virulence." (PMID 20828378, 2010). "However, in the serum of SARS-CoV-2–infected macaques, we found a transient virus infection–related increase in 2 interferon-γ–driven inflammatory cytokines, CXCL10 and CXCL11, and an increase of CCL2, whereas interleukin-6 was elevated in only 1 animal." (PMID 40876955, 2026). "Concordantly, circHOMER1 dampened the transcription of IFNB1 and CXCL10 after viral infection." (PMID 40662732, 2025). "Interestingly, increased production of CCL5 and CXCL10 is also observed from CNS-resident cells following viral infections of the CNS, with CXCL10 linked to effector T cell trafficking to the CNS." (PMID 40613088, 2025).
viral infection (continued). "As expected, CXCL10 levels were elevated in all groups, as this chemokine is upregulated by type I and II IFNs following viral infections and plays a key role in the pathogenesis of viral infections." (PMID 40295813, 2025). "As a result, CXCL10 has been identified as a promising biomarker for viral infections." (PMID 39861921, 2025). "CXCL10 and IL1B encoding proteins are the pro-inflammatory cytokines that are involved in a wide variety of processes, and thereby play an important role during viral infections by stimulating the activation and migration of immune cells to the infected sites." (PMID 39698468, 2024). "In addition, the inflammation‐related molecules such as CXCL2 and CXCL10 were upregulated in the mid‐aged ECs upon viral infection." (PMID 38098255, 2024). "CXCL-10 is a powerful chemoattractant for T cells and natural killer cells, which kills virus-infected cells in the mucosa, thus contributing to defense against viral infections." (PMID 39538325, 2024). "Knockdown of ISG56 reduced CXCL10 mRNA and protein levels upregulated by viral infection." (PMID 38923445, 2024). "Furthermore, a defect in the IFN-γ-downstream IP-10/CXCL10 cytokine results in refractory viral infections." (PMID 38254990, 2024). "Also, a transcriptome study of neuron cultures after viral infection detected upregulation of Ccl4, Cxcl10, Oas1, Irf1, and Irf7, an important modulator of the type I interferon process." (PMID 38189117, 2024). "Indeed, we did observe elevated levels of the chemoattractant CXCL10 and pro-inflammatory IL-6, both essential cytokines for initiating migration of several innate and adaptive immune cells and responding to viral infection, respectively." (PMID 37724882, 2023). "Viral infection may lead to the release of CXCL10 in the bronchial epithelium, which activates mast cells and allows them to migrate to airway smooth muscles to exacerbate airway inflammation and bronchoconstriction in asthma." (PMID 36829591, 2023). "Thus, acute viral infections were identified in three (samples C, G, and H) of the eight CXCL10-high samples." (PMID 36586415, 2023). "Because virus infection such as Epstein–Barr virus has been reported in SLE patients, we next infected EBI2‐deficient macrophages with the DNA virus herpes simplex virus 1(HSV‐1), which again resulted in a dramatic up‐regulation of Ifnb and Cxcl10." (PMID 37469011, 2023). "Moreover, intraperitoneal injection of RSQ in mice is useful in vivo model of ssRNA virus infection, which induces pro-inflammation, such as CXCL10 in the periphery and central nervous system, and virus infection-like illness." (PMID 36673407, 2023). "Furthermore, viral infection increased the mRNA expression of cytokines (Il6, Tnf), chemokines (Cxcl10, Ccl2), and interferon-responsive genes (Ifnb1, Ifit3, Irf7, Gbp5 and Isg15)." (PMID 37081549, 2023). "For example, CXCL10, which is upregulated during viral infection, activates eosinophils in vitro." (PMID 35795686, 2022). "This highlights the significance of CXCL10 expression in multiple viral infections that could aid in viral clearance or contribute to disease pathogenesis." (PMID 36366543, 2022). "Furthermore, when the viral infection was linked with a pulmonary pathology (e.g., influenza and SARS-CoV-2), CXCL10 levels were higher than when the infection was associated with a non-pulmonary pathology (e.g., human rhinovirus)." (PMID 35958594, 2022). "Similarly, the IP-10/CXCL10 concentration was reported to increase in response to viral infection in CRSwNP." (PMID 35455762, 2022). "Furthermore, CXCL10 has been shown to induce the migration of T cells and NK cells following viral infections, where it attracts NK cells into the CNS post MHV infection." (PMID 36366543, 2022). "Collectively, our data are in line with the current understanding on CXCL10 in viral infections." (PMID 33494515, 2021).
viral infection (continued). "Specific markers of viral infection such as CXCL10/IP-10 or macrophage activation such as sCD14 may also be more sensitive to HCMV reactivation than CRP." (PMID 33500556, 2021). "The upregulation of CXCL10 was an innate response induced by viral infections." (PMID 33494515, 2021). "Then in vitro assays verified that virus infection, simulated by Poly(I:C), could promote the secretion of CXCL10 and CXCL16." (PMID 32532953, 2020). "Our results strongly suggest that the CXCL10/CXCR3 axis may play a critical role in the comorbid effect of peripheral viral infections on the progression of major neuropathological diseases." (PMID 32265633, 2020). "Our present study demonstrated that increased serum levels of CXCL10 appeared before the virus reached the brain, possibly reflecting viral infection of peripheral tissues and organs during the first phase of disease; however, the exact source of this chemokine remains elusive." (PMID 31699097, 2019). "IP10/CXCL10 was raised in all viral infections included in our study." (PMID 32116981, 2019). "The main cytokine indicative of viral infection in our study was IP10/CXCL10." (PMID 32116981, 2019). "In addition, IFN-γ potentiated CXCL10 expression via the NF-κB-related pathway against viral infection." (PMID 29681974, 2018). "Chemokine CXCL10 was selected as known to be induced by TLR-3 activation in viral infections." (PMID 29361613, 2018). "Similarly, the expression of the chemokines Cxcl9 and Cxcl10 by TLR3 tolerized macrophages correlates with the role of these factors in CD8+ T cell recruitment to sites of viral infection, cells that have a critical anti-viral activity." (PMID 29867935, 2018). "Both neurons and astrocytes appear to be important producers of CXCL10 during viral infection." (PMID 30442185, 2018). "Viral infection results in the secretion of IFNs, which promotes upregulation of CXCL10." (PMID 29156834, 2017). "Moreover, fibroblast like cell produce type I IFN and CXCL10 after stimulation with double stranded RNA, perhaps contributing to the pathogenesis of viral infections." (PMID 28775743, 2017). "We found that PMN chemoattractant genes Cxcl2 and another chemokine Cxcl10, had significantly reduced expression in Opn−/− mice compared to WT controls at 4 d.p.i., which may be attributed to milder viral infection in the brain." (PMID 28680095, 2017). "Our results showed that CXCL10 mRNA expression levels were significantly upregulated at 6 h and 24 h p.i., suggesting that it might contribute to the neuropathogenesis after viral infection." (PMID 27525278, 2016). "CXCL10, which reacts with the chemokine (C-X-C motif) receptor 3 on Th1 cells and stimulates T cell and NK cell chemotaxis, and Fas were also expressed following viral infection." (PMID 26659307, 2015). "Recently, studies using cultured human lung organ and bronchial/tracheal epithelial cells showed that an influenza virus infection induces considerable amount of CXCL10, a chemokine that attracts activated natural killer and Th1 cells, which have an essential role in virus infection clearance." (PMID 24708855, 2014). "CXCL10 plays an important role in resistance to and elimination of viral infections." (PMID 24692853, 2014). "IP-10 (CXCL10) is a Th1 cell-related chemokine which is important in the recruitment of Th1 cells involved in host immune defense against intracellular pathogens such as viral infection." (PMID 23346216, 2012). "It is expectable that a mild viral infection of the mucosal epithelium in vivo promotes further airway inflammation by triggering epithelial CXCL10 production, allowing accumulation of activated T lymphocytes which in turn enhance epithelial chemokines and cytokines production." (PMID 22022590, 2011).
viral infection (continued). "The CXCL10/11high basal cells also had upregulated mRNA encoding for complement components (C1R and C1S), MHC class I (HLA-A, HLA-B, HLA-C, and B2M), and metalloproteases MMP2 and MMP13, the latter reducing repair during viral infection in bronchial epithelial cells." (PMID 40980495, 2025). "In pulmonary inflammation caused by viral infection, the loss of RIPK3 reduces the secretion of various inflammatory cytokines and chemokines, especially CXCL10 (also known as interferon-γ-inducible protein 10 [IP-10]) and chemokine ligand 2 (CCL2; monocyte chemoattractant protein 1 [MCP-1])." (PMID 38684668, 2024). "Although accumulating evidence have supported the redundant functions of CXCL9 and CXCL10 in controlling recruitment, differentiation and proliferation of immune cells in various disease, such as tumor development and viral infections, their activities in S. aureus infection remain unclear." (PMID 39001897, 2024). "Therefore, expression of ISG56 may play a protective role against viral infection by increasing CXCL10 expression; however, the increase in CXCL10 that mediates the migration of lymphocytes may also induce rejection in renal transplantation." (PMID 38923445, 2024). "A variety of genes such as OAS2, PARP9, OASL, IFIT2, IFI3, CCL8, CXCL10, etc., were highly upregulated and correlated with high viral load, suggesting that innate immune response genes were activated in a viral load dose response manner to control the viral infection." (PMID 37333115, 2023). "However, some of our data in the hamster and AGM models is suggestive of cell-intrinsic viral RNA effects on CXCL10 expression, which may be due to these samples being obtained at earlier times of viral infection." (PMID 37737611, 2023). "Therefore, an increase in CXCL10 characterizes many ssRNA virus infections." (PMID 36673407, 2023). "CXCL10 is a pro-inflammatory cytokine and is known to be involved in a wide variety of processes, such as chemotaxis and activation of immune cells, making it an important player in viral infections by stimulating the activation and migration of immune cells to infected sites." (PMID 37214419, 2023). "Therefore, targeting CXCL10 could be a possible therapeutic modality against many viral infections, as well as against tumor development." (PMID 36366543, 2022). "Moreover, CXCL10 was expressed within tissues following viral infections, suggesting an essential role for this chemokine in host defense by contributing to the lymphocyte activation, migration, and infiltration of specific T cell subsets within the sites of infection." (PMID 36366543, 2022). "Moreover, CCL5 and CXCL10 are chemokines frequently released upon viral infection." (PMID 34386007, 2021). "Interestingly, activation of type-I IFN signaling in brain endothelial and epithelial barriers results in CXCL10 release into the brain parenchyma and this signaling cascade was recently correlated to “sickness behavior,” a common set of symptoms due to viral infections." (PMID 31474994, 2019). "Therefore, eosinophils are likely to contribute to the development of asthma exacerbation through several mechanisms, including activation by Th2 cytokines, such as IL-5 or GM-CSF or by virus infection-related proteins, such as CXCL10, and interaction with other cells, such as neutrophils." (PMID 30323811, 2018). "Similarly, although CXCL9 and CXCL10 expression are vital to the host’s response to CNS viral infections, persistent increases in astrocyte secretion of CXCL10 correlated with increased disease severity, while CXCL10 neutralization improved neurological outcome." (PMID 26860080, 2016). "While previous studies have demonstrated that IL-17A signaling directly induces CXCL10 production in esophageal cell lines, and the production of IL-17F is necessary for CXCL10 expression in hepatic viral infection models, whether the IL-17 axis induces CXCL10 during NAFLD remains undefined." (PMID 26895034, 2016).